HMGA2 (high mobility group AT-hook 2)
Diseases named in the same sentence as HMGA2 in open-access papers (continued):
Sharing a sentence is not in itself a finding about the gene and the disease.
tumor (continued). "HMGA2 is frequently overexpressed in various cancer types and plays critical roles in tumor development, including promoting cell cycle progression, DNA repair, EMT, and chemoresistance, making it a pivotal regulator of cancer progression and a potential therapeutic target." (PMID 38493165, 2024). "This could validate HMGA2 as an accurate, easily measurable cancer marker that reflects the protein status within the tumor tissue." (PMID 39085703, 2024). "Furthermore, we highlight the role of HMGA2-induced EMT in promoting tumor growth, migration, and invasion." (PMID 38361784, 2024). "HMGA2 has been previously reported to act as a functional antagonist of PARP1 inhibitors in tumor cells, while DOT1L, a predictor of poor prognosis in most solid tumors, remains relatively understudied, with its role in PARP inhibitor-resistant OC still unidentified." (PMID 38778348, 2024). "Consequently, numerous studies have investigated the role of HMGA2 protein in various signal transduction pathways involved in tumor development." (PMID 39085703, 2024). "High HMGA2 expression levels may correlate with tumor aggressiveness and treatment response, guiding clinicians in selecting appropriate treatment strategies." (PMID 39085703, 2024). "Next, we examined the effect of HMGA2 knockout on tumor cell migration using wound healing assay." (PMID 39591457, 2024). "HMGA1 and HMGA2 are two important members of it and play an important role in tumor progression." (PMID 38405614, 2024). "Furthermore, higher HMGA2 levels are significantly correlated with advanced tumor grade, lower survival rate, and poor prognosis in patients with BC." (PMID 38753081, 2024). "Likewise, contemporary investigations have illuminated HMGA2’s analogous involvement in tumor development." (PMID 39591457, 2024). "This link between HMGA2 overexpression and elevated vascular density may potentially contribute to tumor formation." (PMID 38473181, 2024). "In addition, high expression of HMGA2 has been reported to increase the invasion and metastasis potential of tumor cells.Abe et al24 compared HMGA2 protein expression between normal-appearing pancreas, CP, and PDAC groups." (PMID 37787719, 2023). "In addition, it has been reported that HMGA2 can induce EMT in tumor cells by interfering with the cell cycle." (PMID 38304037, 2023). "PRCC transcriptomic data from the TCGA database revealed that compared to non‐tumor tissues, the expression of high‐mobility group protein A2 (HMGA2) was upregulated in tumor tissues, and patients with high HMGA2 expression exhibited shorter overall survival times." (PMID 37283291, 2023). "Among the 87 cases in the entire neoplasia cohort, 27 (31%) were positive for HMGA2." (PMID 37787719, 2023). "Furthermore, SPC-high cells produced organoids with Hmga2-high cells after passaging in culture or transplantation in vivo and vice versa, suggestive of plasticity between the tumor organoid cell states." (PMID 36993454, 2023). "Interestingly, we found that the K tumor organoids are almost depleted of the Hmga2-high Group 4, raising the possibility that KrasG12D mutation alone cannot drive AT2 cells to acquire the Hmga2-high Group 4 state, at least at the 7 day timepoint." (PMID 36993454, 2023). "MiR-let-7a targets HMGA2 (high-mobility group AT-hook 2 protein), an oncogene that controls proliferation, invasion, and cell apoptosis and has recently been described as a prognostic factor of tumor grade in some cancers." (PMID 37047725, 2023). "Notably, silencing HOTTIP resulted in the upregulation of miR-124-3p which, in turn, attenuated invasion, migration, and tumor proliferation by targeting HMGA2 through Wnt signaling modulation." (PMID 37888209, 2023). "The results confirmed that HMGA2 was upregulated in OSCC and associated with tumor malignancy." (PMID 37237385, 2023). "Immunohistochemically, we showed that HMGA2 was expressed only in the nuclei of tumor cells." (PMID 37787719, 2023).
tumor (continued). "Moreover, high levels of HMGA2 have been correlated with tumor invasion, tumor size, and high Ki-67 in pituitary adenomas." (PMID 35955787, 2022). "Collectively, our findings suggest exosomal HMGA2 from EBV-positive NPC cells promotes tumor metastasis by targeting multiple endothelial TJ and promoting EndMT, which highlights secreted HMGA2 as a potential therapeutic target and a predictive marker for NPC metastasis." (PMID 35388172, 2022). "The patient with a CR had a tumor with high HMGA2 expression, despite the low data quality." (PMID 36568239, 2022). "Besides, HMGA2 in BC tissues (n = 64) was upregulated compared with tumor-adjacent normal tissues (n = 64)." (PMID 36180890, 2022). "Interestingly, it has been demonstrated that IMP3 ribonucleoprotein complexes contain HMGA2 mRNA, preventing miRNA-directed mRNA decay during tumor progression." (PMID 34997006, 2022). "The pro-tumor role of HMGA2 has been widely reported in multiple cancers including LUAD." (PMID 36324565, 2022). "Inhibition of HMGA2 reversed the effects of circ_0000658 overexpression on tumor growth in vivo." (PMID 35031054, 2022). "In addition, the study found that IGF2BP2 and its co-expressed genes (HMGA2, PHLDB2, and YEATS2) are all associated with a variety of TICs in OSCC tumor samples." (PMID 35129592, 2022). "However, inhibition of miR-205-5p or elevation of high-mobility group A2 (HMGA2) can reverse the function of inhibited circ_0007331 in tumor cells." (PMID 35400282, 2022). "However, the mechanisms by which tumor-derived HMGA2 modulates tumor microenvironment in CRC remain poorly understood." (PMID 34976223, 2022). "HMGA2 was reported to take part in the regulation of tumor development." (PMID 35400282, 2022). "The inability of tumor cells to repress CD24 and the wider expression of HMGA2 during the differentiation process may favor in vivo tumor growth." (PMID 35884847, 2022). "Moreover, miR-766-5p inhibition and overexpression of HMGA2 rescued the tumor-suppressing roles of circSHKBP1 downregulation in LSCC." (PMID 35502885, 2022). "We found a higher HMGA2 expression in tumor tissue compared with peritumoral tissue." (PMID 34302528, 2021). "Moreover, nuclear expression of HMGA2 was significantly stronger in lymph node nuclei than primary tumor cell nuclei." (PMID 34302528, 2021). "Interestingly, the tumor cells with the lowest expression of HMGA2 have indicated more apoptosis than HMGA2 overexpressed cells." (PMID 34356120, 2021). "Moreover, the accumulating evidence suggests that HMGA2 protects tumor cells from apoptosis via activating phosphoinositide-3-kinase (PI3K/Akt) pathway and increasing Bcl2 expression to exert an anti-apoptotic effect." (PMID 34356120, 2021). "Suggestively, our results indicated that SNX15, ATP2A1, PDCD10, BET1, and HMGA2 could serve as a biomarker signature of tumor progression and metastasis in CHOL patients." (PMID 34831096, 2021). "HMGA2 is a transcription factor that is overexpressed in tumor development." (PMID 33498521, 2021). "Cytoplasmic HMGA2 has been also found by others in various tumor entities." (PMID 34302528, 2021). "CX‐4945, a CSNK2A1 inhibitor, could inhibit the phosphorylation of HMGA2 and sensitize tumor cells to cisplatin." (PMID 34115920, 2021). "Importantly, along with nuclear expression of HMGA2 we also detected distinct cytoplasmic localization of HMGA2 in tumor cells." (PMID 34302528, 2021). "Firstly, we found a positive correlation for cytoplasmic HMGA2 expression with lympho-vascular invasion and, secondly, we found a significantly stronger nuclear expression of HMGA2 in cancer-positive lymph node nuclei compared to primary tumor cell nuclei." (PMID 34302528, 2021). "GPC3 and HMGA2 are upregulated in all tumor clusters compared with background liver." (PMID 34497364, 2021). "Interestingly, HMGA2 staining was significantly stronger in lymph node nuclei compared to the individual corresponding nuclei of the primary tumor (p = 0.049)." (PMID 34302528, 2021).
tumor (continued). "However, a trend towards lower tumor growth in the HMGA2 knockdown group appeared late in the experiment." (PMID 34680349, 2021). "Furthermore, HMGA2 is able to inhibit the induction of tumor cell apoptosis by the protection of telomerase and has been noted as one of the most important transcription factors that have a key role in cell development along embryogenesis." (PMID 34356120, 2021). "In addition, the IHC results showed that inhibiting the expression of circ-HMGA2 can inhibit the process of EMT in tumor tissues." (PMID 33762580, 2021). "Moreover, we explored the complex interplay between different species of RNAs, in which miR-370-3p exerts a tumor-suppressor function in GSCs by targeting HMGA2 and HIF1A mRNAs, genes involved in EMT and hypoxia." (PMID 32443824, 2020). "Indeed, not only did HMGA2 suppression repress tumor genesis, but ectopic HMGA2 expression promoted tumorigenesis in our in vivo model." (PMID 32489328, 2020). "However, there has been a dearth in studies investigating the mechanistic potential of HMGA2-induced neoplasms in LAM." (PMID 32365712, 2020). "Increased evidence has suggested that HMGA2 could be involved in tumor growth, cancer cell differentiation, and stem cell self-renewal." (PMID 32577156, 2020). "Hmga2 is a driver of tumor metastasis and Igf2bp2 is a downstream target gene." (PMID 32793490, 2020). "Our verification of the circ_100565/miR-506-3p/HMGA2 axis only remained at the cell level, and whether miR-506-3p inhibitor or HMGA2 overexpression can also invert the regulation of circ_100565 on NSCLC tumor growth in vivo is still unknown." (PMID 32425695, 2020). "It is suggested that epithelial tumor cells, upon HMGA2 induction, might become more responsive to the TGFβ ligand typically present in tumor microenvironments, signaling for increased tumor metastasis." (PMID 32365712, 2020). "Interestingly, marked upregulation of HMGA2 was observed with E2, P4 or combinations of both in the tumours analyzed at 24 hours." (PMID 32251338, 2020). "The findings displayed that VB‐mediated let‐7g‐5p might inhibit the tumour growth of GBM in vivo via down‐regulating HMGA2." (PMID 32000296, 2020). "High mobility group AT-hook 2 (HMGA2) is a member of HMGA family, and previous studies have shown that HMGA overexpression is often found in malignant tumors, which is often associated with the transformation of tumor cells." (PMID 32425695, 2020). "Also, lupeol administration exerts its anti-tumor effect by overexpression of miR-212-3p to suppress the expression of HMGA2 in OS cells." (PMID 32883329, 2020). "The speculated mechanism of which is that H19 potentiates the expression of HMGA2 (high mobility group AT-hook 2), a key regulator of tumor metastasis, by targeting let-7." (PMID 33520725, 2020). "In particular, we identified CNV in chr 12q leading to HMGA2/CDK4 upregulation, a high rate of SV in chr 7q leading to several in-frame gene fusions, a high rate of KMT2C mutation, and gene mutation signatures specifically related to MAS tumor progression." (PMID 32351899, 2020). "In addition, we have seen for the first time that ovarian steroids increased HMGA2 mRNA levels in the 5 UL tumours analyzed." (PMID 32251338, 2020). "In addition, certain tumor types were synonymous with HMGA2 gene translocations involving specific chromosomes, as observed with chromosome 14 in uterine leiomyomata and pulmonary chondroid harmatomas." (PMID 32365712, 2020). "Indeed, the HMGA2 gene was identified, because it was found to be rearranged in several tumours at the level of the third intron and was only subsequently completely cloned and characterized." (PMID 31979076, 2020). "A previous study indicated that miR-490-3p expression was negatively correlated with HMGA2 in OS, and the tumor-suppressed function of miR-490-3p could be reversed by overexpression of HMGA2 in OS cells." (PMID 32883329, 2020).
tumor (continued). "In a word, let-7a may have anti-tumor effects via targeting HMGA2 but whether this may work in LSCC is unclear." (PMID 32432318, 2020). "Besides modulating TWIST expression directly, miR-219-5p was reported to target the oncofetal protein, high-mobility group A2 (HMGA2), and reduced subcutaneous tumor growth in vivo." (PMID 32993038, 2020). "Similar to HMGA2, although the expression of IGF2BPs is normally restricted to embryonic stages, they are re-expressed upon malignant transformation, playing roles in the maintenance of cancer stem cells and the promotion of tumor growth." (PMID 31484926, 2019). "Thus, the cellular HMGA2 protein levels determined the efficacy of PARP inhibitor olaparib in blocking PARP activity in human tumor cells." (PMID 30289618, 2019). "Upon MMS‐induced DNA damage, we were unable to detect PARylated HMGA2 in Parp1 knockout MEFs but readily showed HMGA2 PARylation in wild‐type MEF cells demonstrating that PARP1 was responsible for DNA damage‐induced PARylation of HMGA2 in our tumor cell models." (PMID 30289618, 2019). "To determine whether HMGA2 was a target of PARylation, we treated our tumor cell models with MMS and performed co‐immunoprecipitation studies with an antibody specific for poly‐ADP‐ribosylated sites." (PMID 30289618, 2019). "HMGA2 is intensively reported as an oncogene to promote tumor progression in multiple carcinoma." (PMID 31481527, 2019). "As expected, HMGA2 was upregulated in tumor tissues compared to the adjacent tissues." (PMID 31581665, 2019). "Therefore, cell cycle assays were carried out and revealed that the cells were mostly arrested in G0/G1 phase, implying a reduction in the number of dividing tumour cells following HMGA2 knockdown." (PMID 31053152, 2019). "miR‐9 may play a crucial role in the proliferation, migration and cell cycle progression of HCC cells in vitro and in HCC tumor growth in vivo via targeting HMGA2." (PMID 31408273, 2019). "Taken together, these observations suggest that miR‐9 may suppress tumor growth by inhibiting HMGA2 expression." (PMID 31408273, 2019). "HMGA2 mRNA also is the established target of a tumor suppressor let-7 miRNA family." (PMID 31692974, 2019). "Treatment of mice with Hmga2-wildtype and Hmga2-deficient tumours with gemcitabine did not uncover a significant impact of Hmga2-deficiency on gemcitabine sensitivity." (PMID 30228296, 2018). "Notably, high mobility group AT-hook 2 (HMGA2) has been recognized as a driving factor of tumour metastasis." (PMID 29391048, 2018). "Therefore, the rescue experiments implied that HMGA2 is a functional target of miR-302a-5p/367-3p and ectopic expression of HMGA2 can reverse the anti-tumour effect of miR-302a-5p/367-3p." (PMID 29391048, 2018). "By all metrics, from overall survival to histology of primary tumours and metastases to the presence and number of CTCs and DTCs, Hmga2-deficiency did not perturb PDAC development in any significant way." (PMID 30228296, 2018). "The expression of HMGA2 was increased along with the tumor differentiation grades." (PMID 29596435, 2018). "They found that the forced expression of HMGA2 could increase the colony forming capacity in intestinal organoids and that the haploinsufficiency of HMGA2 significantly decreased the tumor incidence in villin-Lin28b mice." (PMID 30018946, 2018). "Recently, increasing evidences have suggested that HMGA2 protein could participate in aggressive tumor growth, stem cell self-renewal, DNA damage response, and tumor cell differentiation." (PMID 29997523, 2018). "As an oncogene, HMGA2 regulates cell proliferation, the cell cycle and apoptosis, and it is involved in the regulation of invasion and metastasis, which are key processes in tumour progression, such as ovarian tumours, breast adenocarcinoma and lung cancers." (PMID 29391048, 2018).
tumor (continued). "let-7 is a founding member of the microRNA (miRNA) family, postulated to function as a tumor suppressor gene by negatively regulating the post-transcriptional expression of multiple oncogenes including Ras, Myc, and Hmga2, as well as other cell cycle regulator genes in humans." (PMID 29699519, 2018). "In these studies, the level of HMGA2 expression was all detected in collected tumor tissues." (PMID 29997523, 2018). "From the assay used to determine the function of HMGA2 and miR-302a-5p/367-3p in vivo, we found that the overexpression of miR-302a-5p/367-3p combined with the knockdown of HMGA2 effectively reduced the volume and weight of transplanted tumours in nude mice." (PMID 29391048, 2018). "In addition, several recent studies demonstrated that HMGA2 overexpression, both in the tissues and blood of patients with cancer correlated with poor tumor differentiation, positive lymph node metastasis, and advanced stage, indicating a poor prognosis." (PMID 29416690, 2018). "In vivo, the volume and weight of tumours were lower in the sh-HMGA2 group than in the sh-NC group." (PMID 29391048, 2018). "Neither overall survival nor histology of the tumours in mice treated with gemcitabine were significantly affected by Hmga2-deficiency." (PMID 30228296, 2018). "Furthermore, HMGA2 promoted tumor growth compared with the vector control, and group with HMGA2 overexpression exhibited marked chemoresistance in the response to 5-FU treatment." (PMID 29515783, 2018). "Furthermore, in squamous skin cancer mouse models, Hmga2 was found to be dispensable for tumour initiation and progression." (PMID 30228296, 2018). "These indicated that HMGA2 play important roles in tumor progression." (PMID 29245924, 2017). "Indeed, HMGA2 knockdown resulted in reduced tumour cell migration and network formation in vitro and reduced the activity of MMP." (PMID 28533522, 2017). "The effects of HMGA2 on tumour growth in nude mice are reflected by growth curves." (PMID 28533522, 2017). "Next, we detected the expression of VE-cadherin to analyse the correlation between HMGA2 and VE-cadherin not only because Twist1 promotes VM formation by targeting its promoter but also due to its frequent overexpression in tumour tissues and its importance in both tumour invasion and VM formation." (PMID 28533522, 2017). "We found that miR-125b-5p could negatively regulated the expression of HMGA2, and knockdown of HMGA2 partially phenocopied the effects of miR-125b-5p overexpression on the tumor cell phenotypes." (PMID 28968424, 2017). "Let‐7i is a member of the let‐7 family of tumor suppressor miRNAs that inhibits cancer cell proliferation, survival, migration, and invasion by downregulating a variety of oncogenes such as myc, Ras, HMGA2, and Lin28B." (PMID 28079973, 2017). "Importantly, we further found that miR-125b-5p negatively regulated HMGA2, and knockdown of HMGA2 partially phenocopied the effects of miR-125b-5p overexpression on the tumor cell phenotype." (PMID 28968424, 2017). "The highly invasive tumor cell line (CL1-5) had strong HMGA2 expression." (PMID 29079814, 2017). "Its two targets appear to be RAS and HMGA2, oncogenic proteins in a variety of tumours." (PMID 28377929, 2017). "This was the highest frequency of HMGA2 overexpression in any tumor type studied." (PMID 28592321, 2017). "Stage is a classical prognostic factor for WT patients, we then evaluated whether HMGA2 expression was related with tumor stage." (PMID 29383160, 2017). "Furthermore, in the xenograft mouse models, tumours derived from HMGA2 overexpressing cells were much larger than those form the control group." (PMID 28533522, 2017). "Of note, two of the four tumors with HMGA2 rearrangements also harbored an FGFR2M186T mutation, raising the possibility that these events may cooperate in tumor development." (PMID 29084941, 2017). "In addition, our results suggest that HMGA2 was more likely to participate in tumor invasion and metastasis than tumorigenesis." (PMID 29245994, 2017).